PPARG (peroxisome proliferator activated receptor gamma)
Diseases named in the same sentence as PPARG in open-access papers (continued):
Sharing a sentence is not in itself a finding about the gene and the disease.
tumor (continued). "This analysis revealed a significant anti-correlation between PPARγ expression in tumor cells and infiltration of CD8+ T cells into the tumor compartment." (PMID 28740126, 2017). "Taken together, these results demonstrate that PPARG inhibition in AML cells results in significantly impaired migration and clonogenic potential, two key functional properties of tumor cells." (PMID 28275008, 2017). "Since B16F10 cells express PPARγ, it is possible that rosiglitazone treatment suppressed B16F10 tumor growth through direct effects on the tumor cells." (PMID 29228682, 2017). "However, in certain contexts the presence of PPARγ may actually promote tumor growth." (PMID 29181019, 2017). "Accordingly, we demonstrate that while PPARG agonism accelerates AML growth, PPARG antagonism is inhibitory, strongly suppressing AML proliferation and tumor‐initiating capacity, via a TGFB‐mediated inhibition of PDGFB and CTGF." (PMID 28275008, 2017). "We tested pro-tumor genes expression and PPARγ activity (FABP4 expression) in coculture, we can see both PPARγ knockout and PPARγ (D64A) THP-1 cells downregulated pro-tumor genes expression, however, PPARγ activity is not impaired in PPARγ (D64A) THP-1 cells." (PMID 28974683, 2017). "PPARγ agonists reduce mammary carcinogenesis, which correlates with induction of PTEN and BRCA1 tumor suppressor activity, as well as reduction of inflammation via the Cox2/Ptgs2 pathway." (PMID 28077942, 2016). "In the present study, we examined the PPARγ expression in tumor cells of patients with MLS by IHC and confirmed PPARγ mRNA expression levels using quantitative RT-PCR." (PMID 27401457, 2016). "Knockdown of PPARγ gene in PC3-M cells by siRNA significantly reduced the average size of tumours formed in nude mice by 99% and tumour incidence by 90%, and significantly prolonged the latent period by 3.5 fold." (PMID 26814431, 2016). "This study aimed to investigate the prognostic value of PPARγ in HCC and its role in inhibiting tumor progression, namely, HCC cell growth, migration, and angiogenesis." (PMID 27483249, 2016). "Here we sought to understand the gene regulatory networks that control tumor cell metabolism and proliferation in a temporal manner by generating a thorough characterization of the gene regulatory effects of LXR and PPARG signaling." (PMID 27401066, 2016). "Intensity of staining for PPARγ in tumours produced by PC3-M-PPARγ-si-H cells (Fisher Exact test, p = 0.002) or PC3-M-PPARγ-si-M cells (p = 0.02) was significantly weaker compare to those produced by parental cells." (PMID 26814431, 2016). "Increased interaction between β-TrCP and Cyclin D1 was shown to promote Cyclin D1 protelysis in LNCap cells with exposure of peroxisome proliferator-activated receptor-γ (PPARγ) agonist STG28 and thereby contributed to its anti-tumor activity." (PMID 27854312, 2016). "Consistent with the previous report of PPARγ suppression of iNOS expression, we similarly observed that ligand-mediated, sumoylated PPARγ decreased the expression of COX2 and TNFα, and thus suppressed tumor cell migration and growth." (PMID 26244663, 2015). "Results from current studies, however, demonstrate that TR4 can function as a tumor enhancer via regulating the stem cell population and EMT to promote PCa initiation if PPARG is deleted or its function is suppressed by the GW9662 inhibitor." (PMID 25859557, 2015). "In human bladder cancer, PPARγ agonists troglitazone and 15d-PGJ2 have shown to inhibit tumor growth." (PMID 24672773, 2014). "Consistent with previous observations that PPARγ agonists usually inhibit the proliferation of tumor cells, we found that treatment with 15d-PGJ2, a natural endogenous ligand of PPARγ, significantly inhibited cell proliferation in all examined HCC cell lines." (PMID 24023668, 2013). "Finally, the role of PPARγ in cells in the tumor microenvironment remains unclear." (PMID 22934105, 2012).
tumor (continued). "In contrast, BADGE induced nuclear localization and activation of PPARγ leading to apoptosis in ECV304 cells, whereas BADGE induced apoptosis in different tumor cell lines in a PPARγ-independent manner." (PMID 22763116, 2012). "Furthermore, PPARg ligands have been shown to inhibit tumor growth and progression in preclinical models of lung cancer, by modulating various cellular processes in cancer cells, stromal cells and tumor microenvironment, through PPARg crosstalk with other signaling pathways." (PMID 22701659, 2012). "PPARγ downregulates matrix metalloproteinase-7 (MMP-7) and induces MMP inhibitors expression, suppressing tumor cell invasion." (PMID 22848209, 2012). "In this paper, we have demonstrated that knocking down PPARγ in the ATC cell line HTh74 not only inhibited in vitro cell growth, but also reduced in vivo tumor growth in flank and orthotopic xenografts." (PMID 22194735, 2011). "Since other members of this family, such as PPARG, exhibit a tumor suppressor-like phenotype, it is possible that PPARA can act as a tumor suppressor in hematological malignancies." (PMID 20052266, 2010). "We also established that rosiglitazone (a PPARγ agonist) elevated MKP-1 expression level in NSCLC cells and inhibited tumour metastasis." (PMID 20226009, 2010). "Decreased expression of peroxisome proliferator activated receptor-γ (PPARγ) and high levels of the proinflammatory enzyme cyclooxygenase-2 (COX-2) have been observed in many tumor types." (PMID 18769553, 2008). "PPARG is a gene which has been shown to play a pivotal role in the processes of cellular differentiation, adipogenesis, and several reports connect PPARG status with neoplastic processes suggesting that PPARG may act as a tumor suppressor for some tissues and in some cellular contexts." (PMID 18822129, 2008). "BADGE has been shown to serve as a PPARγ agonist in RAW 264.7 cells, human monocytes and in some epithelial cells and as an inducer of apoptosis in some tumor cells." (PMID 18261208, 2008). "Recent in vitro studies have shown that PPARγ can regulate the transcription of phosphatase and tensin homolog on chromosometen (PTEN), a known tumor suppressor." (PMID 19096712, 2008). "Interestingly, nuclearexpression of PPARγ was significantly reduced in a majority of the patientswhose pre-rosiglitazone PPARγ scores were 1+ or 2+ and therefore assessable forincreased or decreased levels of expression, which raised the possibility of aPPARγ mediated response in the tumor tissue." (PMID 19125177, 2008). "PPARγ is expressedin human non-small-cell lung cancer (NSCLC) and smallcell lung carcinoma, and theexpression of PPARγ has beencorrelated with tumor histological type and grade." (PMID 18769553, 2008). "The expression of PPARγ has been demonstrated in NSCLC and was correlated with tumor histological type and grade." (PMID 17597835, 2007). "mRNA levels of c/EBPβ, PPARγ, c/EBPα and SREBP-1c fell significantly in tumour-bearing mice and there was a striking 100-fold reduction in c/EBPα (P<0.01) compared with freely fed controls." (PMID 17047651, 2006). "Adaptive browning, regulated by transcriptional drivers such as PRDM16, PPARγ, and PGC1-α, mitigates metabolic inflammation, enhances insulin sensitivity, and may exert tumor-suppressive effects." (PMID 41848823, 2026). "Therefore, we suggest investigating PPARG antagonists (e.g., GW9662, as supported by recent OSCC preclinical studies) to disrupt this tumor-stromal crosstalk." (PMID 41596281, 2026). "In the premenopausal cohort, across tumor receptor types (HER2‐negative, ER+, TNBC), patients with low PPARγ expression have lower survival, especially in the ER+ and TNBC cohorts where there is marginal significance; in the HER2‐negative cohort, there are minimal differences across the two groups." (PMID 41236441, 2025).
tumor (continued). "Targeting PPARγ, a key regulator of metabolic reprogramming and stemness in hepatic CSCs, or modulating the PPARγ/PPARα balance that finely tunes the differentiation/retrodifferentiation process in HCC deserves further investigation for anti-tumor therapy." (PMID 41249163, 2025). "Mechanistically, these observations align with bioinformatic analyses highlighting PDGFRβ as an upstream regulator of multiple downstream effectors—PPARγ, VEGFA, ANG-2, VIM, COL1A1, and Cadherins all integral to tumor progression, angiogenesis, and cellular plasticity." (PMID 40282535, 2025). "In ER+BC, PPARγ forms a complex with ERα, antagonizing the PI3K/AKT survival pathway, suppressing aromatase expression, and reducing local estrogen synthesis, thereby inhibiting tumor growth.Riboflavin plays a pivotal role in cellular energy metabolism." (PMID 41415282, 2025). "In cancers, where a sustained energy supply and lipogenic signaling are essential for tumor growth and survival, DHA-induced restriction of energy influx, together with the downregulation of Pparγ, Fabp4, Fasn, Gpr120, and Slc2a4, disrupts key pro-tumorigenic pathways." (PMID 41373668, 2025). "Furthermore, FABP5 regulates the expression of VEGF through PPARγ and enhances the expression of other angiogenic factors, including EGF and IL‐6, thereby promoting tumor angiogenesis." (PMID 40178066, 2025). "FABP4 promotes tumor cell proliferation and EMT through the PPARγ/β-catenin axis." (PMID 40717587, 2025). "In addition, rosiglitazone, another agonist of PPARγ, was found to impede colorectal cell proliferation by activating PTEN (a tumor suppressor) and regulating the expression of phosphatidylinositol 3-kinase (PI3-kinase)." (PMID 39875357, 2025). "Beyond the PPARγ/NF-κB/IL-8 axis, PEDF has been shown to bind the catalytic β-subunit of F1-ATP synthase present on the surface of various tumor cell lines inhibiting ATP production and decreasing the viability of both endothelial and tumor cell." (PMID 40001923, 2025). "In thyroid cancer, PPARγ activation promotes the transcription of tumor suppressor genes such as p21 and PTEN, thereby inhibiting proliferation and differentiation, and exerting anti-tumor effects." (PMID 41153831, 2025). "PPARγ inhibits the tumor immune escape of non-small-cell lung cancer (NSCLC) by inducing programmed death ligand 1 (PD-L1) protein autophagic degradation in lysosomes, suppressing NSCLC tumor growth by increasing T-cell activity." (PMID 40573305, 2025). "The regulators in C1 LYZ+ tumor cells were mainly FOXA2, PDX1, GATA6, and PPARG." (PMID 40230840, 2025). "In vitro experiments indicated that interferon gamma (IFNγ), a key immune cytokine in MSI tumours, downregulates FABP1 expression, while activation of PPARγ (with rosiglitazone) can restore it, suggesting a regulatory loop influenced by inflammatory signalling." (PMID 41149452, 2025). "The PPARγ agonist pioglitazone prevents HCC and reduces macroscopic tumor nodules." (PMID 38920644, 2024). "Here, we found that inhibiting PPARγ in OSCC can promote ferroptosis by upregulating HMOX1 and promoting disulfidptosis through the upregulation of SLC7A11 and the subsequent recruitment of additional cDCs and CD8+ T cells to inhibit tumor development." (PMID 38786003, 2024). "In both estrogen-receptor-negative and estrogen-receptor-positive breast cancer, PPARγ is a tumor suppressor." (PMID 39765861, 2024). "Several studies have shown that PPARγ antagonist or siRNA-mediated silencing of PPARγ expression failed to abrogate certain anti-tumor effects of TZDs." (PMID 38397426, 2024). "After neoadjuvant immunotherapy, a higher AUCell of the PPARG regulon was found in the pCR group and tumour tissues than in the nonpCR group and normal tissues, respectively." (PMID 38773508, 2024).
tumor (continued). "We therefore hypothesized that POM121 participates in the transport of PPARγ across the NPC to regulate its transcriptional activity on genes involved in metabolic and tumor control." (PMID 38177114, 2024). "However, only one gene, AKT2, presented a significant increase in tumor tissue (p = 0.01), and four genes showed a significant increase in normal tissue (AKT2, AKT3, PPARG, and PTEN; p ≤ 0.04)." (PMID 38505269, 2024). "In this study, we demonstrate that in the CSP group, PPARG consistently exhibits increased expression in the normal tissue surrounding the HSCC tumor (LFC = 2.00 ± 0.31), while its expression in the tumor tissue displays significant variation (LFC = 0.41 ± 0.80)." (PMID 38505269, 2024). "According to the experimental results in vivo and in vitro, we speculated that PPI promotes the combination of RXRα and PPARγ by targeting ZBTB16, leading to the inhibitory effect on the malignant phenotype of tumor cells." (PMID 39182119, 2024). "The expression of PPARγ in the foamy macrophage component of the LTGCT was noticed regardless of the size of the tumor." (PMID 38882990, 2024). "Truncated PPARγ undergoes cytoplasmic-mitochondrial translocation, which inhibits MCAD and FAO and promotes lipid accumulation, leading to reprogramming of TAMs to the M2 phenotype and proliferation of tumor cells." (PMID 37004014, 2023). "In addition, our study indicates that PPARγ plays an underrecognized role in maintaining pericyte phenotype, such that early exposure to PPARγ-directed therapy could potentially limit their contribution to the pool of tumor-supporting myofibroblasts in developing tumor microenvironments." (PMID 37816052, 2023). "In mouse xenograft models, rosiglitazone, an activator of PPARγ, demonstrated anti-tumor effects as an early intervention, but not as a treatment, with tumor formation repressing PPARγ and rendering stromal cells insensitive to ligand." (PMID 37816052, 2023). "Furthermore, according to these 7 key genes (ABCB1, CAP1, EGFR, ITGB1, MAPK1, PPARG, SNCA), we plotted the KM curves to show the survival state of high and low expression groups in tumor samples from the TCGA-PAAD dataset." (PMID 37857015, 2023). "The S100A4/PPARγ pathway enhances CD36-mediated FA uptake and thus the pro-tumor activity of TAMs." (PMID 37004014, 2023). "Notably, Ercolano G., found that blocking PPARγ in IL-33-dependent tumors such as CRC can greatly suppress the IL-33-stimulated release of type 2 cytokines from ILC2, thus decreasing tumor migration." (PMID 37686309, 2023). "PPARG may regulate tumor-infiltrating cells in the TME through different pathways, thereby affecting tumor development." (PMID 37334066, 2023). "Q11 does not directly affect tumor cells but blocks the tumor‐promoting effect of microglia/macrophage (M/Mφ) in the tumor microenvironment through PPARγ‐mediated activation of the STAT‐1 and NF‐κB pathways and inhibition of the STAT‐3 and STAT‐6 pathways." (PMID 37283464, 2023). "Moreover, MALAT1 upregulated the expression of CD36 and liposynthases (PPARγ, PGC1α, SREBP-1C, FAS, and ACC), enhancing unsaturated fatty acid synthesis and uptake, thereby promoting tumor cell progression." (PMID 37533434, 2023). "However, increasing evidence has indicated that PPARg and its activator PGC-1a can also act as tumour promoters." (PMID 36681687, 2023). "The master regulator of mitochondrial biogenesis, PPARG, as well as PPARGC1A and the downstream effectors and transcription factors NRF1 and BACH1, are upregulated in various metastases as compared to the primary tumor or to the target site." (PMID 38039408, 2023). "Treatment of established xenograft tumors with rosiglitazone failed to activate PPARγ target genes and no longer suppressed tumor growth." (PMID 37816052, 2023).
tumor (continued). "Importantly, blocking PPARγ activation by GW9662 diminished 15d-PGJ2-induced autophagic cell death, which highlighted the critical role of autophagy in 15d-PGJ2-mediated tumor suppression of lactotroph PitNETs." (PMID 37250410, 2023). "PPARγ protein cannot be decomposed if it is not activated by a ligand, which accumulates abnormally in tumor cells." (PMID 35911149, 2022). "Although this study did not explore a tumor model, the presented results open up new avenues for research on cancer and various pathologies, as well as PPARγ activity and CCNA1." (PMID 35256739, 2022). "Activation of PPARG expression may inhibit the progression of LSCC through the regulation of LSCC upstream regulators and downstream marker genes involved in tumor cell proliferation and protein polyubiquitination/ubiquitination." (PMID 35805937, 2022). "The transcriptional activity of PPARγ was deactivated by the oncogene, resulting in the induced expression of the lipolytic gene FABP4, which was accompanied by a reduction in lipid droplets and tumor growth." (PMID 36532833, 2022). "PPARγ levels showed differences between non-tumor adjacent tissue and tumor tissue, being tumor tissue PPARγ levels higher than non-tumor adjacent tissue." (PMID 36139645, 2022). "It is reported that Lactobacillus produces short-chain fatty acids (SCFAs), which reduce the expression and function of intestinal P-glycoprotein (P-gp) and upregulate breast cancer resistance protein (BCRP), leading to tumor suppression via the inhibition of HDAC/NF-κB and activation of PPARγ." (PMID 35300424, 2022). "By inhibiting NF-κB, TZD-activated PPARγ substantially lowers the expression of pro-inflammatory, pro-angiogenic, and pro-metastatic signaling molecules in CAFs, including IL-6, IL-8, CXCR4, MMP2, and MMP9, which further dampens pro-tumor crosstalk in the TME." (PMID 33946986, 2021). "Breast tumor cells produce lactate which can activate G2A in TAMs causing intracellular activation of the peroxisome proliferator-activated receptor γ (PPARγ), which keeps macrophages in a non-aggressive M2-like state and enhances tumor growth." (PMID 34440817, 2021). "The failure of PPARG negative tumours to develop suggests that PPARG is essential for tumour growth and progression in vivo." (PMID 33654198, 2021). "Together, these findings suggest that arachidonic acid metabolism might make contribution to M2-TAMs formation via PPARγ-OXPHOS modulation, thus promote tumor progression." (PMID 34149684, 2021). "Aside from these, PPARγ has a hand in the propagation of the signaling, mainly through interacting with the well‐known tumor suppressor protein PTEN (translated from the PTEN gene; OMIM number *601728) that counteract tumor cells and reduce their survival." (PMID 34549887, 2021). "Here, the authors show in mice that when an activated form of PPARg is expressed in basal bladder cells tumours do not form, however in the presence of injury the basal cells differentiate into luminal cells." (PMID 34697317, 2021). "In addition, to evaluate the therapeutic potential of PPARγ inhibition in CRC development and progression, we treated tumor-bearing mice with T0070907." (PMID 33953160, 2021). "The anti-inflammatory activity of PPARγ in cells of the myeloid lineage has been described as crucial in governing proinflammatory cytokine production, myeloid-derived suppressor cell (MDSC) expansion, immunosuppression, and tumor progression." (PMID 34111028, 2021). "Tumours lacking any PPARG expression fail to develop, and any tumours that do develop express PPARG." (PMID 33654198, 2021). "Our data supported this opinion and also suggested that besides tumor cell-derived PGE2, macrophage-derived PGE2 may also make contribution to M2-TAMs polarization through PPARγ-OXPHOS pathway." (PMID 34149684, 2021).